LAMB3 (laminin subunit beta 3)
Diseases named in the same sentence as LAMB3 in open-access papers (continued):
Sharing a sentence is not in itself a finding about the gene and the disease.
tumor (continued). "Other highly upregulated genes with tumor suppressor and/or cell cycle inhibitory activities are LAMB3, LAMC2, and IL1RN, which were increased by 10- to 15-fold." (PMID 34349241, 2022). "LAMB3 at mRNA and protein level was significantly down-regulated in sphere-derived tumor compared with adherent cells-derived tumor (P value <0.05)." (PMID 36415640, 2022). "Other highly upregulated genes with tumor suppressor and/or cell cycle inhibitory activities are laminin-5 (LAMB3, LAMC2) and IL1RN, which were increased by 10- to 15-fold." (PMID 34349241, 2022). "For example, the tumor-suppressor miR-218 targeted LAMB3, a laminin-332 component of the basement membrane which influences cell adhesion, migration and invasion in SCCC through cytoskeleton organization." (PMID 33917510, 2021). "Suppressing the expression of LAMB3 diminishes the metastasis of tumor cells and sensitizes them to the cytotoxicity of CP therapy." (PMID 32503307, 2020). "We observed that the PDPN and LAMB3 proteins were specifically expressed in OSCC cells at the tumor periphery." (PMID 31238980, 2019). "We also confirmed that the restoration of miR-24-3p inhibited PDAC growth and LAMB3 expression in a subcutaneous xenotransplanted tumor model in vivo." (PMID 32039003, 2019). "Our in vivo experiments confirmed that miR-24-3p repressed tumor proliferation and inhibited the expression of LAMB3." (PMID 32039003, 2019). "The LAMB3 knockdown group showed a slower increase in tumor volume and weight than did the control group." (PMID 30850586, 2019). "miR-24-3p is a novel regulatory factor of LAMB3 and exerts anti-tumor effects by suppressing LAMB3 expression in vitro and in vivo." (PMID 32039003, 2019). "According to the total immunohistochemistry (IHC) score (percentage of positive cells x staining intensity), LAMB3 was expressed at higher levels in PDAC tumor tissues than in adjacent normal tissues." (PMID 30850586, 2019). "Using a phospho-RTK array, we found that c-MET acts upstream of Akt, indicating that LAMB3 leads to tumor invasion via Akt activation induced by the HGF/c-MET axis in PTCs." (PMID 29426928, 2018). "LM-332 (encoded by LAMA3, LAMB3, and LAMC2) has been linked to tumor invasiveness in various types of cancer." (PMID 29426928, 2018). "As shown in our results, both TPC-1 cells (carrying RET/PTC-1) and B-CPAP cells (carrying BRafV600E) promoted tumor progression via LAMB3/Akt signaling, despite carrying different types of genetic alterations." (PMID 29426928, 2018). "LAMB3 is integral to the invasive and metastatic abilities of several tumor types found in the colon, pancreas, lung, cervix, and prostate." (PMID 29426928, 2018). "Experimental validation showed that MLF1IP, LAMA3 and LAMB3 were progressively increased from tumor initiation to progression." (PMID 30598639, 2018). "Considerably higher expression of LAMB3 protein levels was detected in all five tumor samples relative to the normal tissues." (PMID 29426928, 2018). "The functions of LAMB3 as an oncogene or a tumor suppressor in ESCC carcinogenesis need to be explored in further work." (PMID 28904855, 2017). "LAMB3 (Laminin Subunit β 3), as a component of laminin-332 (LM-332), plays a pivotal role in facilitating basement membrane (BM) degradation, a critical step in enabling tumor cells to invade surrounding tissues." (PMID 40149492, 2025). "APOE may influence T cell function by modulating lipid metabolism and immune regulation, while LAMB3 may participate in tumor immune responses by affecting T cell migration and localization." (PMID 41343534, 2025). "Upregulation of LAMB3 has been observed in pancreatic ductal adenocarcinoma wherein it regulates cell cycle arrest and apoptosis, thus altering tumour behaviour in terms of multiplication, aggression, and metastasis by modulating the PI3K/Akt signalling pathway." (PMID 41139196, 2025). "Cellular experiments demonstrated that LAMB3 promotes malignant behavior of tumor cells." (PMID 37577750, 2023).
tumor (continued). "This also indicates that LAMB3 can serve as potential tumor biomarkers and therapeutic targets." (PMID 37577750, 2023). "As changes in the laminin gene expression have been associated with changes to the immunophenotype of a tumour in different contexts, we also queried the LAMA3, LAMB3, and LAMC2 genes in the TIMER2.0 database to investigate their relationship with tumour-infiltrating lymphocytes." (PMID 37779898, 2023). "On the one hand, tumor cells may act on PCs by secreting oncogenic molecules (ANGPTL4 or LAMB3) to inhibit their antitumor function or promote isotype switching of protumor subtypes." (PMID 37138324, 2023). "Based on these findings, it appears that LAMB3 could be a potential therapeutic target for immunotherapy and tumor prognosis." (PMID 37577750, 2023). "Patients with the upper third LAMA3 (p = 0.01), LAMB3 (p = 0.01) and LAMC2 (p = 0.01) transcript abundance were each associated with a higher histological grade, while high LAMA3 (p = 0.001) and LAMC2 (p = 0.01) were associated with the residual tumour stage." (PMID 37779898, 2023). "Signal transduction from tumor cells of specific states (stress-like and hypoxia-like tumor cells) to PCs, for example, via the LAMB3/CD44 and ANGPTL4/SDC1 ligand/receptor pairs, was validated by spatial transcriptome analysis and associated with poorer OS as well as nonresponse to immunotherapy." (PMID 37138324, 2023). "The mechanism by which LAMB3 is involved in immune regulation is still unknown, and the effect of LAMB3 on tumor immunity also varies depending on the type of tumor." (PMID 37577750, 2023). "Seven ECMGs (i.e. LAMB3, LAMA3, ITGB6, ITGB4, ITGA2, LAMC2, and COL11A1) were identified to be hub genes of PAAD, which were obviously up-regulated in PAAD and considerably linked to tumor stage as well as prognosis." (PMID 36311789, 2022). "Together, PIGR may serve as a powerful prognostic biomarker and putative tumor suppressor by suppressing the AKT-FOXO3/4 axis by downregulating LAMB3 in CRC." (PMID 35992840, 2022). "Furthermore, we evaluated the possible link between the ECMGs and the tumor stage of PAAD, and 8 ECMGs (i.e. FN1, LAMA3, ITGB6, ITGB4, ITGA2, LAMC2, COL11A1, LAMB3) were detected to be significantly associated with tumor stage." (PMID 36311789, 2022). "LAMB3, a subunit of laminin-332, promotes tumor progression, as reported by previous studies." (PMID 35992840, 2022). "Accumulating data show the stimulatory effect of LAMB3 on the viability and growth of tumor cells." (PMID 32503307, 2020). "LAMB3 protein was diffusely expressed in the tumour cells of most MuEp cases." (PMID 32878206, 2020). "The miR-24-3p/LAMB3 axis plays a vital role in tumor progression, and targeting it may represent a novel therapeutic strategy for PDAC." (PMID 32039003, 2019). "LAMB3 knockdown by shRNA significantly reduced p-Akt-S473 levels without altering total Akt protein levels, indicating that LAMB3 could promote tumor invasion by activating the Akt signaling pathway in PDAC." (PMID 30850586, 2019). "Moreover, an analysis of the clinical characteristics of PDAC revealed that high LAMB3 expression was related to more advanced tumor node metastasis (TNM) stage." (PMID 30850586, 2019). "LAMB3 can be found in many different kinds of epithelial tissues and tumor microenvironment." (PMID 30519576, 2018). "The results revealed that the PI3K-AKT pathway was active in tumor cells and that MDFI upregulated the PI3K-AKT pathway by directly regulating LAMB3 and ITGB4." (PMID 38375821, 2024). "Based on the TCGA database, the patients were divided into two groups (Tumor group and Normal group), of which 56 cases were normal controls, and high expressions were also observed on CLDN10, HMGA2, and LAMB3." (PMID 39205691, 2024). "Of note, we observed that CYTOR‐related nodal genes were mainly involved in EMT, p‐EMT or tumor invasion in HNSCC, including LAMB3, PDPN and FNDC3B." (PMID 38032139, 2024).
tumor (continued). "Of note, we confirmed a correlation between the expression levels of perlecan/HSPG2 and LAMB3 or HSPG2 and SRPX and found that it increases during tumor progression." (PMID 39149513, 2024). "The findings presented here show that LAMA3, LAMB3, and LAMC2 are frequently upregulated at the gene and protein levels in PAAD tumours compared with controls and that these increases are related to worse survival outcomes." (PMID 37779898, 2023). "Based on the expression and biological localization analyses of L/R pairs, we identified two L/R pairs (LAMB3/CD44 and ANGPTL4/SDC1) with high reliability between tumor cells and PCs." (PMID 37138324, 2023). "The largest expression differences between tumour and normal samples were observed for LAMA3 (mean fold change; mfc = 21.7, p = 2.1 × 10−61), LAMB3 (mfc = 55.3, p = 7.9 × 10−60), and LAMC2 (mfc = 51.0, p = 3.8 × 10−61) transcripts." (PMID 37779898, 2023). "These analyses identified that LAMA3, LAMB3, and LAMC2 expression levels are increased at the mRNA and protein levels in PAAD tumours with evidence of co-regulation." (PMID 37779898, 2023). "In particular, we noticed that COL1A2, LAMB3, LOX, LTBP2 and S100A6 were significantly upregulated in tumor specimens, when compared with normal tissue." (PMID 35340765, 2022). "Overexpressed in tumor matrix were proteins involved in ECM organization such as LOX, LAMB3, ADAMTSL1 and FBN2." (PMID 35340765, 2022). "To validate the tumor-promoting role of C4 cells, we chose the EMT marker LAMB3 and the C4 highly expressed gene ERO1A as surrogate markers." (PMID 36209225, 2022). "To explore the expression level of LAMB3 in PDAC, we first analyzed the GEO GSE28735 dataset, exploring the mRNA expression profile of 45 matched PDAC tumors and adjacent non-tumor tissues." (PMID 32039003, 2019). "In analogy to the published intratumoral localization of pEMT-signature genes LAMB3 and LAMC2, pERK1/2 and especially Slug were frequently expressed in cells of the leading edge of tumor areas in our cohort." (PMID 30261040, 2018). "Several studies showed Laminin 332 (LAMA3, LAMB3 and LAMC2) to be highly expressed in HNSCC and foster tumor invasiveness, an effect that is reversed when the laminins are repressed by microRNA‐29s." (PMID 27596625, 2016). "The expression level of miR-218 was significantly downregulated in tumor tissues compared with adjacent normal tissues (p = 0.039), whereas LAMA3, LAMB3 and LAMC2 were upregulated in tumor tissues (P = 0.018, p = 0.0029 and p = 0.0009, respectively)." (PMID 23159910, 2012). "Seven of the twelve differential genes found amongst individual tumor ANOVA analyses were common to the linear discriminant gene profile (LD-p54): ANGPLT4, COL1A1, GP2, GPR57, LAMB3, PCDHB9, and PTGER3." (PMID 15836779, 2005). "Therefore, we used publicly available spatial transcriptomic (ST) data to interrogate sub-localizations of fDEGs in tumor core (TC), and leading edge (LE) of oral SCC (external dataset GSE208253), as exemplified for ITGB4, LAMA3, LAMB3, and LAMC2." (PMID 40121428, 2025). "Although SCC tumor cells are known to produce laminin-332 proteins, the expression levels of all laminin-332 genes (Lama3, Lamb3, and Lamc2) were similar between TGF-β-responding and nonresponding tumor cells in vivo." (PMID 31792062, 2019). "Inhibition of LAMB3 abrogated the tumorigenic outcomes of PI3K/Akt signaling pathway activation, including those involving cell cycle arrest, cell apoptosis, proliferation, invasion and migration in vitro, and tumor growth and liver metastasis in vivo." (PMID 30850586, 2019). "Finally, we have shown that LAMB3 regulates the invasive and metastatic potential of PDAC in vivo by mouse tumor xenograft and liver metastasis models." (PMID 30850586, 2019). "Finally, by using a subcutaneous xenotransplanted tumor model, we demonstrated that miR-24-3p overexpression inhibited the proliferation of PDAC by suppressing LAMB3 expression in vivo." (PMID 32039003, 2019).
tumor (continued). "Furthermore, we demonstrated that ZIC1 can suppress the expression of other novel genes (TACSTD2, ANGPT2, LAMB2, LAMB3 and MALAT1 etc.)related to tumor angiogenesis and metastasis." (PMID 21347233, 2011). "Thus, stress-like tumor cells may suppress the antitumor function of CD44+ IgG1 PCs and promote tumor progression by secreting LAMB3." (PMID 37138324, 2023). "Notably, we found p-EMT tumor cells (p-EMT sub-cluster) that highly expressed CDH1 (E-cadherin), keratin KRT14/16/17, TP63 (Tumor protein p63), and basement membrane ECM glycoprotein- Laminin family (LAMC2, LAMB3, LAMA3...)." (PMID 35742914, 2022). "Furthermore, six tumor progression genes (GNAI2, ODC1, APP, TNFRSF12A, BASP1, and LARP6) and nine migration and metastasis‐related genes (MSN, FLOT1, LAMB3, MYL9, ITGB1, FTH1, TPM4, and PMEPA1), which could explain the invasive characteristics of SCC, were identified." (PMID 40776410, 2025). "Promoter methylation was lower in PAAD than normal pancreatic tissues for all three genes (LAMA3 normal β:0.43, tumour β:0.34, p = 2.8 × 10−9; LAMB3 normal β:0.65, tumour β:0.53, p = 8.6 × 10−7; and LAMC2 normal β:0.44, tumour β:0.38, p = 0.04)." (PMID 37779898, 2023). "The results showed that the expression levels of ITGA2, ITGB6, LAMA3, LAMB3, and LAMC2 are significantly correlated with the tumor stage of PAAD patients, while the expression levels of COL1A2 are not correlated with the tumor stage of PAAD patients." (PMID 35899199, 2022).
infection (3 papers, 2018 to 2023). The state of being infected such as from the introduction of a foreign agent such as serum, vaccine, antigenic substance or organism. "Uniquely in the colon, strong downregulated interactions were driven by epithelial laminins (LAMB3 and LAMC2) and integrins, with T cells and macrophages as the main immune cell types targeted upon infection." (PMID 35501398, 2022).
head and neck tumor (1 paper, 2019). "IHC database showed the protein expression of TGFBI, SPP1, and LAMB3 in head and neck tumor tissues were up-regulated compared with normal tissues." (PMID 31485443, 2019).
vascular disorder (1 paper, 2020). A general term used to describe any disease affecting blood vessels]. "Five proteins, THBS2, LASP1, LAMB3, ITGAV, and COL11A1A, were selected according to their GO classification, the Kyoto Encyclopedia of Genes and Genomes (KEGG) pathways in which they can be involved and their relationship with AAA or vascular disorders." (PMID 32605321, 2020).
LAMB3 also shares sentences with these, for which no sentence is quoted: skin disorder (3 papers); bladder urothelial cancer (2); breast invasive carcinoma (2); cervical adenocarcinoma (2); non-small cell lung carcinoma (2); prostate adenocarcinoma (2); recessive dystrophic epidermolysis bullosa (2); adenocarcinoma (1); adenocarcinoma in situ (1); adenoma (1); amoebiasis (1); anaplastic thyroid carcinoma (1); asthma (1); Blepharophimosis (1); breast tumors (1); childhood asthma (1); cholangitis (1); chorioamnionitis (1); colon adenocarcinoma (1); Congenital muscular dystrophy type 1A (1); ductal carcinomas (1); endometrial cancer (1); Epicanthus inversus (1); esophageal cancer (1); familial candidiasis (1); hemoglobinopathies (1); Hurler-Scheie syndrome (1); Hypodontia (1); Hypoplastic amelogenesis imperfecta (1); ichthyosis (1).
A further 19 diseases each share a sentence with LAMB3 in 1 paper.